AQP1 (aquaporin 1 (Colton blood group))
Diseases named in the same sentence as AQP1 in open-access papers (continued):
Sharing a sentence is not in itself a finding about the gene and the disease.
tumor (continued). "In this connection, a remarkably impaired growth of implanted tumors was demonstrated in AQP1 null mice, with reduced tumor vascularity and an extensive necrosis." (PMID 19584911, 2009). "This study highlighted the downregulation of AQP1 in tumor tissues compared to healthy tissues." (PMID 40305202, 2025). "Therefore, the role of AQP1, AQP3 and AQP5 in tumor development is closely associated with their peroxiporin function." (PMID 39941100, 2025). "Consistently, the expression of multiciliation regulators Gmnc, TAp73, and Foxj1, as well as CP epithelial markers Ttr and Aqp1, were significantly reduced in tumor cells irrespective of Sox2 loss." (PMID 40128799, 2025). "The downregulation of AQP1 in OSCC may suppress tumor cell motility, yet its specific biological functions in this malignancy require further investigation." (PMID 40386053, 2025). "The modulation of these genes’ expression was analyzed, according to the age range and gender of the patients and the grade of tumor invasiveness and aggressiveness, and was further correlated with the gene expression of AQP1, AQP3, AQP5, and AQP9, previously reported." (PMID 40305202, 2025). "AQP1 interacts with key intracellular signaling pathways, suppressing apoptosis while amplifying pro-migratory and pro-invasive signals, thereby promoting tumor progression." (PMID 41463012, 2025). "Additionally, nutritional factors secreted by MSCs, such as C–C motif chemokine ligand 5 (CCL5) and aquaporin 1 (AQP1), can promote tumor migration and invasion." (PMID 40600065, 2025). "In addition to carrying the Braf gene, chromosome 6 carries several genes that are highly expressed in the LNM and tumor populations (Aqp1, Col1a2, Cav1, Cav2, Ptn, RaRes2, Fkbp9, Actg2, Ybx3, Mgp, Sox5, Kcna1, and Ptms)." (PMID 40571713, 2025). "Given the inverse correlation between AQP1 protein abundance and apoptosis reported in several tumor cell types, we tested whether elevated levels of AQP1 could contribute to apoptosis resistance in SuHx PASMCs." (PMID 39175041, 2024). "C-Myc is frequently overexpressed in tumour cells and may effectively induce the expression of E-Box comprising genes, hence elevating AQP1 expression." (PMID 38336645, 2024). "Emerging evidence has recently identified that AQP-1-driven tumors resist necroptosis and apoptosis, which may contribute to AQP1-mediated tumor proliferation and metastasis." (PMID 38307919, 2024). "This implies that the silencing of AQP1 may facilitate the formation of a hypoxic environment, thereby influencing tumour cells towards apoptosis." (PMID 39440058, 2024). "Nevertheless, the role of AQP1 enriched in the cytoplasm remains elusive, which might be essential to decipher the mechanisms of tumor progression and metastasis." (PMID 38307919, 2024). "AQP1 was found to boost endothelial cell migration and, in association with overexpression of AQP4 to regulate water influx and extracellular matrix interaction leading to tumor cell membrane filopodia formation, mechanisms linked to metastasis progression." (PMID 38476871, 2024). "Inhibition of tumor growth and suppression of vasculogenic mimicry formation were observed following AQP1 silencing in vivo, which could be related to reduced tumor aggressiveness, malignancy, and metastasis." (PMID 38476871, 2024). "In a separate study conducted on a melanoma mouse model, there was an observable elevation in the expression levels of HIF-1α, high-molecular weight DNA fragmentation and caspase-3 (CASP3) within the AQP1 siRNA-treated tumour cells in comparison to the control group." (PMID 39440058, 2024). "AQP1 has the ability to work with carbonic anhydrases to block hydrogen ions (H+) from entering the cell, resulting in enhanced lactic acid generation, preventing tumour cytotoxic oedema and reduces the pH of the extracellular space." (PMID 38336645, 2024). "Inhibition of AQP1 contributes to a reduction of VM, thereby suppressing tumor growth." (PMID 38791252, 2024).
tumor (continued). "Moreover, elevated levels of AQP1 can enhance the invasive and metastatic potential of tumor cells, potentially inducing VM." (PMID 38791252, 2024). "This suggests that overexpression of AQP1 may be a consequence of angiogenesis and perform a significant role in tumor edema formation or clearance." (PMID 36672280, 2023). "In summary, these results suggest that AQP1 overexpression may enhance tumor progression by interacting with the transcriptional regulation networks governed by FOXO4, MAZ, and E2F TFs." (PMID 38057925, 2023). "In addition, AQP1 is involved in the effusion or edema fluid development that stimulates tumor angiogenesis." (PMID 36672280, 2023). "Silencing of AQP1 in mice has been shown to reduce tumor growth and angiogenesis." (PMID 36672280, 2023). "Such AQP1 inhibitors probably have potential effects on tumor progression." (PMID 36803413, 2023). "Notably, AQP1 is preferentially upregulated in areas of astrocytomas where tumor cell infiltration occurs, hinting at its potential involvement in tumor angiogenesis." (PMID 37762642, 2023). "A representative study reported that AQP1 may enhance the migratory ability and invasiveness of tumor cells by mediating the Wnt/β-catenin signaling pathway and stabilizing the cadherin/β-catenin/Lin-7/F-actin complex on cell membranes." (PMID 37334171, 2023). "The degree of inhibition was directly related to the potency of the AQP1 ion channel blockage, suggesting that the ion channel properties of AQP1 alone might be sufficient for facilitating tumor cell migration in certain cases." (PMID 37762642, 2023). "In our previous research, we found that the ultra-high b-value DWI could match AQP1 expression of tumor and accordingly speculate AQP1 may be a potential biomarker for prognosis." (PMID 37334171, 2023). "MIA tumor cells exhibited high expression of AQP1 and AGTR2 and a basal‐like molecular character." (PMID 37991139, 2023). "In contrast, under the condition of AQP1 inhibitors, the migration and invasion of BMSCs‐mediated tumor cells were blocked, indicating that the HCC cell malignant behavior may be caused by the recruitment of BMSCs into the TME through AQP1 participation." (PMID 34981659, 2022). "At the same time, the increased expression of AQP1 was significantly related to better OS and DFS in ccRCC patients, which might indicate that AQP1 was a promising tumor suppressor gene for ccRCC patients." (PMID 35245343, 2022). "Importantly, robust expression of AQP1 was detected among proliferating tumor microvessels in resected cancer samples." (PMID 35847914, 2022). "Several reports have shown that AQP1 overexpression in tumor cells may increase tumor invasiveness and angiogenesis, all of which contribute to tumor expansion." (PMID 36389709, 2022). "An imbalance in AQP1 could indicate a possible involvement in tumor angiogenesis and cell proliferation." (PMID 36230654, 2022). "AQP1 enhances tumor cell angiogenesis by signaling downstream of estrogen receptors, while, at the same time, estrogen can increase the expression of AQP1 through transcriptional regulation of the AQP1 promoter." (PMID 35847914, 2022). "Furthermore, aqp1 gene disruption in mice with tumor cell implantations and siRNA silencing of AQP1 in the chick embryo chorioallantoic membrane impaired angiogenesis." (PMID 35163313, 2022). "In addition, among angiogenic markers, the water channel aquaporin (AQP)‐1 expressed in peripheral vascular endothelial cells is involved in physiological and pathological angiogenesis, as well as tumour metastasis and progression." (PMID 35122387, 2022). "With the progress of the tumor stage, the expression levels of AQP1/2/4/6/7/9 gradually increased." (PMID 35245343, 2022). "Especially, AQP1 gene is highly expressed in renal tubules and microvessels, choroid plexus, ciliary epithelium, corneal endothelium, pain-processing C-fibers, and vascular endothelium, tumor vessels and red blood cells." (PMID 35300109, 2022).
tumor (continued). "In addition, cytoplasmic expression of AQP1 negatively correlated with prognosis but positively correlated with histological grade, tumor size, lymph node metastasis, and recurrence or distant metastasis." (PMID 36212456, 2022). "AQP1, which is mostly expressed in the membrane of microvessels, could indicate the extent of neovascularization or angiogenesis of the tumor, and higher AQP1 expression in HCC usually indicates a worse prognosis." (PMID 35111225, 2022). "AQP1 depletion in MMTV-PyVT mice reduced both tumor growth and lung metastasis." (PMID 36212456, 2022). "It has been proposed that the reduced AQP1 expression is an indication of tumor de-differentiation." (PMID 35741021, 2022). "For example, the aqp1 gene promoter contains a consensus HIF-1α binding motif; AQP1 mRNA and protein levels are elevated under conditions of low oxygen, supporting the presumption that AQP1 activity can be regulated by the interplay of growth factors within the tumor microenvironment." (PMID 35163313, 2022). "We previously hypothesized that AQP1 further migrations and aggressive tumor cell behavior (Huo, to be published)." (PMID 33467498, 2021). "AQP1 may behave as an oncogenic biomarker for numerous types of cancer that is able to sustain tumor pathogenesis through facilitating cell proliferation, migration, and angiogenesis." (PMID 33980862, 2021). "Recent discoveries on involvement of AQP1 in cell proliferation and migration have suggested that AQP1 could play a key role in tumor biology." (PMID 33644043, 2021). "Expression of AQP1 can functionally facilitate tumor cell migration and is up-regulated by hypoxia." (PMID 33644043, 2021). "The ADCuh at the center of the tumor showed a small positive correlation with AQP1, AQP4 and Ki67." (PMID 34712604, 2021). "Migrating tumor cells express elevated AQP1 levels and a hypoxic biochemical phenotype." (PMID 33644043, 2021). "The present study revealed both RIPK1/RIPK3/MLKL and RIPK1/caspase-8/caspase-3 pathways were inhibited in TNBC tumor samples and AQP1-expressing cell lines, which is in agreement with our presumption that both RIPK1-dependent necroptosis and apoptosis are attenuated by AQP1." (PMID 33980862, 2021). "Because AQP1 is expressed in both membrane and cytoplasm of breast cancer cells, but RIPK1 is exclusively localized in the cytoplasm, the localization of AQP1 and RIPK1 in MDA-MB-231, a human TNBC cell line, and 4T1, a mouse TNBC cell line, was assessed respectively by immunofluorescence staining." (PMID 33980862, 2021). "This shows that AQP1 indeed furthers the ability of the tumor cells to migrate." (PMID 33644043, 2021). "Elevated AQP1 might be a key driver in transitioning stable tumor cells to migrating tumor cells in a hypoxic microenvironment." (PMID 33644043, 2021). "Our experiments strongly suggest that elevated AQP1 might be a key driver in transitioning stable tumor cells to migrating tumor cells in a hypoxic microenvironment." (PMID 33644043, 2021). "Moreover, Aqp1 was also described to be involved in tumor migration, invasion and angiogenesis in glioblastoma." (PMID 32054826, 2020). "It has been reported that AQP1 is involved in cell migration, angiogenesis, and tumor growth." (PMID 32903818, 2020). "AQP1 is highly expressed in microvascular endothelial cells, vascular smooth muscle cells and non-vascular endothelium, and has recently been proposed as a novel promoter of tumour angiogenesis." (PMID 33256119, 2020). "In MEC, AQP1 may be important for the maintenance of the vascular net, which is essential for the transport of nutrients, thereby promoting tumor growth." (PMID 32075009, 2020). "AQP1 gene silencing inhibited tumor cell growth, suggesting that AQP1 could represent a potential therapeutic target." (PMID 32075009, 2020).
tumor (continued). "Meanwhile, the higher percentile of ADCaqp and AQP1’s expression (75th and 97.5th) may represent the most malignant part of a tumor, which features remarkable differences among different patients." (PMID 32576929, 2020). "AQP-1 is highly expressed in tumor cells of different origins, especially in aggressive tumors." (PMID 33209198, 2020). "AQP1 expression was observed in vascular endothelium throughout the tumor stroma." (PMID 32075009, 2020). "We suggest that AQP expression may be involved in MEC tumorigenesis; AQP1 expression in tumor vasculature could facilitate nutrition for sustained neoplastic growth." (PMID 32075009, 2020). "AQP1 is related to tumor cell migration, invasion, and angiogenesis." (PMID 32256525, 2020). "Consistent with prior studies, we found that AQP1 is expressed in GBM tumor cells." (PMID 32253832, 2020). "While it is tempting to hypothesize that AQP1 contributes to the aggressiveness of these tumours, it is possible that high expression of APQ1 is a consequence of the higher pressure that exists inside the tumour." (PMID 32065471, 2020). "There were significant changes in AQP1 and 3 expression at different tumor stages." (PMID 33271827, 2020). "Thus, it is possible that miR-146a-5p is an effective target for the management of tumor progression via AQP1, as a novel anti-cancer therapy." (PMID 31285693, 2019). "It is already shown that AQP1 plays a role in the growth, angiogenesis and metastasis of tumours." (PMID 31374984, 2019). "The effect of Rg3 epimers on the inhibition of proliferation of TNBC cell lines was specific to MDA-MB-231, suggesting that basal-like claudin-low or mesenchymal type tumours, with a high AQP1 expression, might be better candidates for treatment with SRg3." (PMID 31374984, 2019). "Furthermore, clinical studies have shown that some TNBC tumours have higher levels of AQP1 expression and an expression correlated with a poorer prognosis." (PMID 31374984, 2019). "Expression of aquaporin 1 (AQP1), the first molecular water channel described, has been reported to be associated with a poor prognosis, especially in later stages of several solid tumors, when one can assume that hypoxia within the tumor is increasing." (PMID 31600976, 2019). "In vivo, reduced angiogenesis mediated by AQP1 inhibition may additionally contribute to induction of tumour cell apoptosis through hypoxia." (PMID 31013775, 2019). "Previous studies have revealed the positive regulation of AQP1 in tumor progression and demonstrated that AQP1 suppressors could repress biological activities of various tumors, including the growth of tumor cells, cell motility, and angiogenesis." (PMID 31285693, 2019). "This would suggest that AQP1 is regulated by mechanisms within the hypoxic tumor microenvironment." (PMID 31600976, 2019). "Another study reported AQP1 deficiency in mouse mammary tumour virus-driven polyoma virus middle T oncogene (MMTV-PyVT) mice, which spontaneously develop epithelial cancer, results in abnormal tumour microvascular anatomy and reduced vessel density." (PMID 31013775, 2019). "Based on our data, however, AQP1‐dependent reduced angiogenesis could also be due to the reduced amount of MMP2 found in AQP1 siRNA‐treated tumours." (PMID 29044946, 2018). "AQP1 can be expressed by vascular endothelium just like by cancer cells, and blocking aquaporin expression in both tumor cell types may be useful for prognostic purposes." (PMID 29914087, 2018). "Among AQPs, AQP1 plays a pivotal role in tumor angiogenesis and accelerates cell migration." (PMID 30555637, 2018). "AQP1, expressed in peripheral vascular endothelial cells, is involved in tumor angiogenesis." (PMID 29922644, 2018). "The reduced AQP1‐dependent tumour angiogenesis caused a hypoxic condition, evaluated by HIF‐1α significant increase, in turn causing an increased level of apoptosis in AQP1 KD tumours, assessed by CASP3 quantification and DNA fragmentation." (PMID 29044946, 2018).
tumor (continued). "Trying to get inside to the mechanism responsible for the reduced tumour growth and reduced metastatic formation, we have found that reduced AQP1‐dependent neovessel formation is responsible for HIF‐1α increase, reduced expression of MMP2 and increased expression of caspase‐3." (PMID 29044946, 2018). "Previously manufactured drugs such as Bevacizumab and Ranibizumab target VEGF, combining this therapy with an AQP1 inhibitor may allow for further disruption of tumor angiogenesis." (PMID 30555637, 2018). "Researchers have speculated AQP1 stabilises the cadherin/β-catenin/Lin-7/F-actin complex to enhance the migratory and invasive capacity of tumour cells." (PMID 28146084, 2017). "AQP1 may play an important role in the cross-talk between tumour microenvironment and tumour cells together with various growth factors, cytokines and chemokines." (PMID 28146084, 2017). "Although AQP1 is expressed by normal mesothelium, the expression of AQP1 is heterogeneous between tumours and it was initially hypothesised that retained AQP1 expression indicated greater differentiation." (PMID 29104239, 2017). "One proposed mechanism for AQP1-modulated tumour cell migration is induction of osmotic water flow across the plasma membrane by AQP1 in response to an osmotic gradient created by actin depolymerisation and active solute influx at the leading edge of migrating cells." (PMID 28146084, 2017). "Due to its established role in cell migration in MM, and in angiogenesis in other tumour types, we proposed that blockade of AQP1 may inhibit VM in MM cells." (PMID 29104239, 2017). "Ion channel property of AQP1 alone may be sufficient to facilitate tumour cell migration in some cancers." (PMID 28146084, 2017). "Whether TGF-β plays any role in AQP1-facilitated tumour progression remains to be further evaluated." (PMID 28146084, 2017). "AQP1 plays a significant role in tumour cell migration and invasion." (PMID 28146084, 2017). "Alternative mechanism to explain APQ1 modulated tumour cell migration is changes in cell shape and volume of migrating cells during passage through tight environments and generation of hydrostatic forces induced by AQP1." (PMID 28146084, 2017). "Both LaRusso's and Bill's groups demonstrated that AQP1 was observed in cytoplasm of normal and tumor cells and could translocate to cell membrane after certain kind of stimulation." (PMID 26812884, 2016). "Several reports found that AQP1 overexpression in tumor cells may increase tumor invasiveness and angiogenesis." (PMID 27409610, 2016). "In conclusion, our study may provide a potential therapeutic strategy targeting AQP1 to hamper cross-talk between BM-MSCs and tumor cells, thus preventing the establishment of distant metastasis." (PMID 27409610, 2016). "siRNA against AQP1 reversed tumor growth in a murine model of melanoma." (PMID 27023529, 2016). "However it is worth noting that, like other tumours, inhibition of AQP1 by either synthetic blocker or siRNA resulted in decreased MM cell motility and invasiveness in standard culture and spheres." (PMID 27376267, 2016). "Interestingly, in some of these tumours AQP1, a membrane bound protein, was found within the cytoplasm." (PMID 27376267, 2016). "Moreover, BM-MSCs-mediated tumor cell migration and invasion were hampered after treatment with AQP1 inhibitor." (PMID 27409610, 2016). "Blockade of AQP1 expression has been shown to decrease angiogenesis and induce tumor necrosis." (PMID 28036023, 2016). "Very few IDC cases (5.0%, 17/341) showed strong membranous expression of AQP1 with an admixture of less intensive cytoplasmic staining which were ignored in the following studies in order to focus on the role of cytoplasm AQP1 expression in tumor progression." (PMID 26812884, 2016).